CD4 (CD4 molecule)
Diseases named in the same sentence as CD4 in open-access papers (continued):
Sharing a sentence is not in itself a finding about the gene and the disease.
meningitis (52 papers, 2008 to 2025). A disorder characterized by acute inflammation of the meninges of the brain and/or spinal cord. "We also investigated predictors for meningitis in adults in Mozambique and found that CD4 cell count < 100 cells/μL had strong association (aOR = 59, p = 0.001) with meningitis, as also reported in other countries." (PMID 35544535, 2022). "Multivariate logistic regression analysis found that meningitis infection was significantly associated with CD4 count < 100 cells/μL (adjusted Odds Ration (aOR) with 95% CI: 59.0, 18.80–265.27, p = 0.001)." (PMID 35544535, 2022). "In support of this paradigm, our results from HIV-infected patients with low CD4+ T cell numbers were consistent with those from HIV coinfected individuals with meningitis due to Cryptococcus and other or indeterminate causes." (PMID 31871098, 2020). "Low recent CD4 count and turbid CSF were significantly associated with mortality from meningitis in our study population." (PMID 27651801, 2016). "Especially HIV-patients with a CD4-count < 350 cells/μl seem to be under a higher risk of developing cerebrospinal fluid (CSF) and neurological abnormalities (e.g. meningitis)." (PMID 24134407, 2013). "Interestingly, we also detected specific CD4+ T cells in meninges associated with a high frequency of activated B cells and plasma cells." (PMID 39595024, 2024). "On further analysis, considering the interaction between CD4 count and CrAg titers, those with CD4 <50 cells/μL and titer ≥1:160 were at higher risk of meningitis or death (HR = 3.3; 95% CI: 1.1 to 9.8; P = 0.03) compared with those who had a CD4 >50 cells/μL and CrAg titer <1:160." (PMID 30399034, 2019). "A Brazilian study revealed a prevalence of 3.1% (95% CI, 1.0–7.0) in adult HIV-infected inpatients with <200 CD4+ cells/μL, but those with symptomatic meningitis were excluded." (PMID 39057375, 2024). "The prevalence of cryptococcal antigenemia worldwide has ranged from 1.2 to 21.0%, depending on the geographic localization, age, clinical meningitis presence, and CD4+ cell count of the patients included in the study." (PMID 39057375, 2024). "All six survivors had <200 CD4 cells/μL and undetectable VL (P3-P8) at the end of the follow-up (48–78 months); in two of them, antifungal therapy for meningitis was prescribed." (PMID 36547617, 2022). "WHO criteria for CrAg testing were met by 24% of patients (47 of the 200 patients), i.e., 18 with symptoms suggestive of meningitis and an additional 29 presented with CD4 counts less than 100 cells/mm3." (PMID 35193598, 2022). "Both patients were diagnosed with Cryptococcus neoformans meningitis in the setting of untreated HIV infection with CD4+ T cell count < 100/mm3." (PMID 33628553, 2021). "Depletion of T-cells that express CD4 in infected mice resulted in a rapid increase in lung and brain fungal burden that ultimately led to lethal meningitis." (PMID 35186781, 2021). "Although rarely described, it is not surprising that both cryptococcal and streptococcus suis meningitis infections can co-exist in a HIV-infected patient with a low CD4 count." (PMID 34778300, 2021). "For PLHIV presenting with symptoms of meningitis or low CD4+ T cell count, the WHO recommends point-of-care cryptococcal antigen testing (a rapid test for a fungal infection, which causes meningitis in immunocompromised people)." (PMID 33274313, 2020). "Meningitis led to the diagnosis of HIV infection in 5 cases (4 cases with a CD4+ T cell level <200/mm3)." (PMID 26765411, 2016). "The median baseline CD4+ T-cell counts among the hospitalized subjects with meningitis was 28 cells/μL (interquartile range (IQR): 7 to 70) and in the asymptomatic outpatient subjects was 38 cells/μL (IQR: 15 to 70)." (PMID 25078453, 2014). "We screened HIV-infected, antiretroviral therapy naïve persons with symptomatic meningitis (n = 130) and asymptomatic persons with CD4+<100 cells/μL entering into HIV care (n = 399) in Kampala, Uganda." (PMID 25078453, 2014).
meningitis (continued). "The means of CD4 cell counts of the three meningitis patients and the other two cases that died were 99 cells/μl and 34 cells/μl respectively." (PMID 22620862, 2012). "The mean CD4 cell count of three meningitis patients who died was higher as compared to the other two paradoxical TB IRIS patients who died (99 vs.34 cells/μl)." (PMID 22620862, 2012). "World Health Organization recommends screening all PLWHA who have a CD4 < 200 cells/mm3 for cryptococcal antigen to identify those patients who could benefit from preemptive fluconazole treatment prior to the onset of meningitis." (PMID 35139801, 2022). "Notably, cerebrospinal fluid (CSF) and neurological abnormalities (e.g. meningitis) correlate with low (<=350 cells/μl) CD4 cells counts in HIV seropositive individuals." (PMID 24134407, 2013). "Among adult HIV-infected inpatients, targeted serum CRAG screening for patients with symptoms and signs of meningitis and (if known) a CD4 T cell count of less than 200 cells/mm3 may be a reasonable approach in hospitals in sub-Saharan Africa." (PMID 21988905, 2011). "Persons with sterile cultures were more likely to be receiving ART at the time of their meningitis diagnosis, were more likely to have recently initiated ART, and had significantly higher median CD4 counts." (PMID 36675867, 2022). "The keyword with the highest TF–IDF value was ‘readmission’, followed in order by ‘operation’, ‘muscle’, ‘meningitis’, ‘inhibitor’, ‘biopsy’, ‘bath’, ‘aeruginosa’, ‘SARS’, and ‘CD4′." (PMID 34203191, 2021). "Cryptococcal antigen (CrAg) can be detected in the blood before the development of meningitis, and cryptococcal antigenemia is seen more frequently among PLHIV with CD4 cell count < 100 cells/μL than among PLHIV with higher CD4 cell counts." (PMID 32650797, 2020). "Current guidelines recommend screening all people living with human immunodeficiency virus (PLHIV) who have a CD4 count ≤100 cells/μL for cryptococcal antigen (CrAg) to identify those patients who could benefit from preemptive fluconazole treatment prior to the onset of meningitis." (PMID 29514236, 2018). "Current World Health Organization (WHO) guidelines recommend screening all PLHIV who have a CD4 count ≤100 cells/μL for cryptococcal antigen (CrAg) to identify those patients with cryptococcal disease who could benefit from preemptive fluconazole treatment prior to the onset of meningitis." (PMID 29514236, 2018). "The WHO recommends starting ART within 2 weeks of TB treatment, irrespective of CD4 count, except for TB meningitis cases, where a 4–8-week delay is advised." (PMID 40748951, 2025). "At meningitis diagnosis, stimulation with cryptococcal capsule component, glucuronoxylomannan (GXM) elicited consistently lower frequencies of CD4+ and CD8+ T cell memory subsets expressing intracellular cytokines (IL-2, IFN-γ, and IL-17) among subjects who subsequently developed CM-IRIS." (PMID 31126019, 2019). "The WHO recommended package of care for individuals with advanced disease includes CrAg screening for individuals with a CD4 count < 100 followed by fluconazole for CrAg positive people without evidence of meningitis." (PMID 30876400, 2019). "In the context of HIV test-and-treat programs in Uganda, in the absence of CD4 testing, national guidelines currently recommend cryptococcal testing if a person has signs or symptoms of meningitis." (PMID 30629619, 2019). "We included ART-naïve HIV patients with a CD4 cell count below 100 cells/μL and no signs of meningitis in an outpatient HIV clinic in Bandung, West Java, Indonesia." (PMID 24476751, 2014). "Unlike wild type B6 mice, we previously observed that OT-I mice infected intracerebrally with LCMV do not develop neurological symptoms or fatal meningitis due to an inability to mount an LCMV-specific CD8 or CD4 T cell response." (PMID 23737750, 2013).
meningitis (continued). "After completing this study we have implemented screening for cryptococcal antigen for all ART-naïve patients with a CD4 count below 100 cells/μL, followed by lumbar puncture for those with a positive result, and pre-emptive fluconazole treatment for those with a positive result but no meningitis." (PMID 24476751, 2014).
neuroblastoma (51 papers, 2007 to 2025). Neuroblastoma (NB) is the most common solid, extracranial childhood tumor. "Mechanistically, the effect of anti-CTLA4 therapy against neuroblastoma tumors with induced mismatch repair deficiency is CD4+ T cell dependent, as depletion of these cells abolished the effect." (PMID 36068918, 2023). "We have reported CD4 CTL as an important effector of high-risk neuroblastoma, and work by others on adult cancers has indicated that cytotoxic activity of tumor-specific cytolytic CD4 T cells is in part dependent on SLAMF7." (PMID 35525858, 2022). "Together, the data suggest that the effector cells of high-risk neuroblastoma are CD4+ CD3+ NKG2C/E+ CRTAM+, namely CD4 CTLs." (PMID 33968044, 2021). "This study suggests that CD4 CTLs are important effector cells against high-risk neuroblastoma, but their “protective effect” declines over time in part due to the progressive formation of the immunosuppressive TME, leading to the death of the patients." (PMID 33968044, 2021). "High TOX and LAG3 expression was associated with adverse outcome of high-risk neuroblastoma, suggesting the exhaustion of CD4 CTLs." (PMID 33968044, 2021). "By examining a comprehensive RNA-seq gene expression dataset, we detected relatively high levels of CD4 expression in high-risk neuroblastoma tissues." (PMID 33968044, 2021). "The results also suggest that the HLA-E reactive CD4 CTL effector cells are functionally compromised in the TME of high-risk neuroblastoma." (PMID 33968044, 2021). "NTRK1-expressing neuroblastoma cells were most susceptible to both CD4+ and CD8+ CAR T cell-mediated killing, while NTRK2-expressing cells were significantly more resistant." (PMID 32296437, 2020). "Our data suggest that CD4 CTLs are important effector cells against high-risk neuroblastoma." (PMID 33968044, 2021). "Thus, the use of anti-SLAMF7 antibody as therapeutics for high-risk neuroblastoma could enhance effector functions of both CD4 CTL and macrophages." (PMID 35525858, 2022). "In vitro studies have confirmed that anlotinib facilitates tumor vessel normalization through CD4+ T cells, significantly inhibits neuroblastoma (NB) cell growth, and effectively prevents systemic immunosuppression." (PMID 41001046, 2025). "We confirmed the presence of these distinct CD4+ T cells in neuroblastoma by flow cytometry, including high expression of co-inhibitory receptors and Ki-67 in the DUSP4hi cluster." (PMID 38181797, 2024). "This is in line with previous studies, which localized KU70 in the cell membrane and the nucleus of neuroblastoma cells or reported the presence of the KU complex in the cytoplasm of primary CD4+ T cells." (PMID 39769333, 2024). "To determine the role of CD4+ T cells on the activity of anti-CTLA4 therapy against idMMR neuroblastoma tumors, we depleted these cells in immunocompetent animals before the treatment of idMMR tumor-bearing mice with anti-CTLA4 antibody." (PMID 36068918, 2023). "Yet, our results show that despite their presence in human neuroblastoma, CD4+ and CD8+ T cells exhibit features of exhaustion with the expression of at least one inhibitory checkpoint." (PMID 36054452, 2022). "We noticed an important cluster of T cells in our cohort of 10 neuroblastoma patients, including CD4 and CD8 lymphocytes." (PMID 36054452, 2022). "According to the result, we identified that neuroblastoma tissue consisted of relatively high percentages of naive B cells, M0 and M2 macrophages, resting memory CD4 T cells, and CD8 T cells." (PMID 35846139, 2022). "Overall, these data support a model in which the absence of tumor myeloid cell NF‐κB p50 leads to the activation of tumor CD4+ and CD8+ T cells to slow 9464D high‐risk neuroblastoma tumor growth." (PMID 33480449, 2021). "Together, these observations suggest that the anti-neuroblastoma effect of CD4 CTLs relies on the perforin/granzyme pathway." (PMID 33968044, 2021).
neuroblastoma (continued). "We now find that Nb tumors developing in p50(f/f);Lys‐Cre mice have increased total and activated CD4+ and CD8+ T cells and that the combined depletion of both of these T‐cell subsets leads to tumor growth at a rate similar to that seen in control mice." (PMID 33480449, 2021). "IHC staining of neuroblastoma PDXs showed that macrophage depletion significantly increased not only CD3 T cell infiltration but also CD8 to CD4 TIL ratios compared to GD2-EATs, while anti-Ly6G or anti-Ly6C antibody did not affect this ratio." (PMID 34496935, 2021). "To interrogate immune cell infiltration in neuroblastoma gene expression datasets, we inferred the abundance of six common immune cell types, naïve B cells, memory B cells, CD4+ T cells, CD8+ T cells, NK cells, and monocytes." (PMID 34458583, 2021). "It has been reported previously that human neuroblastoma tumors have a fairly substantial FoxP3+ cell infiltration of between 40 and 55% of CD4+ cells, however this was only demonstrated in a small cohort of 3 patients." (PMID 33028899, 2020). "As an example, it was demonstrated that in neuroblastoma patients, antitumor activity and long-term fate of infused T cells is highly concordant with the percentage of CD4+ cells." (PMID 32117253, 2020). "At an effector:target ratio of 2:1, neuroblastoma cell killing was significantly more effective in the presence of CD4+ and CD8+ CD171-specific CAR T compared to control T cells." (PMID 32296437, 2020). "Previous reports showed that CD8+ T-cells prevailed over CD4+ T-cells in the tumor lesions derived from neuroblastoma patients, which meant that the CD4+/CD8+ ratio in tumors was lower than that in peripheral blood." (PMID 29213216, 2017). "Similarly, a study utilized high-intensity focused ultrasound (HIFU) to treat neuroblastoma, which increased intratumoral NK cells, CD4, and CD8 T cells, overcoming therapeutic resistance to achieve long-term survival." (PMID 38830912, 2024). "We also observed an increase of activated CD4+ T cells (CD38+CD4+ T cells) with higher cytotoxic function (CD107a+ CD4+ T cells) in the spleens of previously cured mice that were rechallenged with the poorly immunogenic pMMR neuroblastoma tumor cells." (PMID 36068918, 2023). "We also observed reduced CD4+ T cell levels in idMMR neuroblastoma tumors treated with anti-PD1." (PMID 36068918, 2023). "We also showed, for the first time, that by knocking out the MLH1 gene and inducing MMR deficiency in neuroblastoma tumors they became more immunogenic and highly infiltrated by effector cytotoxic CD8+ and CD4+ T cells, along with an increase in CD39+CD8+ tumor-specific T cells." (PMID 36068918, 2023). "Notably, CD4 T cells with cytolytic signatures and high Eomes expression are found in patients with neuroblastoma, a cancer where CD4 T cells are often more effective than CD8 T cells at promoting tumor destruction." (PMID 36358898, 2022). "This antibody-based approach via agonistic/antagonistic antibodies could in turn augment cytotoxicity of CD4 CTLs and result in a robust anti-neuroblastoma immune response." (PMID 33968044, 2021). "As multiple CD4+ T cell subsets are recognized, we evaluated if we could further narrow down on the precise CD4+ T cell subset that is present in neuroblastoma." (PMID 34458583, 2021). "In another study, it was shown that low expression of CD4+/CD25+/CD127- T reg cells and high levels of IFNγ are associated with improved survival of neuroblastoma patients which are treated with anti-GD2 antibody ch14.18/CHO in combination with interleukin 2 (IL2)." (PMID 32722460, 2020). "The increase of Resting CD4 regulatory T cell is positively correlated with the occurrence and development of neuroblastoma (NB), while the drug papain targets CD4 + T lymphocytes and has a chemotherapy effect on NB." (PMID 40625890, 2024).